SYP (synaptophysin)
Diseases named in the same sentence as SYP in open-access papers (continued):
Sharing a sentence is not in itself a finding about the gene and the disease.
Cognitive impairment (continued). "Moreover, transfer of HGF alleviated cognitive impairment and oxidative stress, and enhanced angiogenesis and synaptophysin levels." (PMID 40564462, 2025). "Nevertheless, it is still unknown how SYP is expressed when OSAS-induced cognitive impairment first appears and worsens." (PMID 38858326, 2024). "Latest study confirmed the presence of cognitive impairment in the mice with hippocampus of Lipin1-deficient, including the worsen spatial learning and memory ability, decreased synapse number, reduced protein levels of BDNF, SYP and PSD95." (PMID 36918862, 2023). "Research has found that SYP decreased and pro-inflammatory factors increased in mice with Alzheimer’s disease, and increasing the expression of SYP can ameliorate the impairment of the synaptic transmission effect in cognitive impairment." (PMID 37205911, 2023). "Combined, these observations suggest that neuroinflammation and synaptic plasticity-associated proteins, such as PSD-95, SYP, and BDNF, may be involved in the cognitive impairment of offspring induced by maternal inflammation during pregnancy." (PMID 38074521, 2023). "A decrease in pro-inflammation cytokine concentrations and an increase in the expression levels of SIRT1, BDNF, PSD-95, and SYP in the hippocampus following resveratrol treatment contributed to reducing the cognitive deficits in offspring mice resulting from maternal immune activation." (PMID 38074521, 2023). "Recently, the mechanism of cognitive impairment has been shown to be related to decreases in SYP, PSD-95, and SNAP-25 levels, which may alter the presynaptic integrity triggered by the loss of dopaminergic degeneration." (PMID 37568205, 2023). "Previous studies from patients with AD have suggested that synaptophysin is more vulnerable than other synaptic proteins such as syntaxin or SNAP-25, and loss of synaptophysin is an early event that correlates with initial cognitive impairment." (PMID 35855335, 2022). "The beneficial effect of SDP on cognition is related to a lower loss of synaptophysin in the brain, consistent with the fact that cognitive impairment can be due to synaptic dysfunction rather than neuronal loss." (PMID 35684013, 2022). "In addition, a previous study has demonstrated that ER stress induces cognitive deficits and alterations in basal synaptic transmission, accompanied by decreased expression of synaptophysin and PSD95 in the hippocampus." (PMID 37676574, 2022). "Multiple sevoflurane exposures reduce synaptic function in the developing cortex and enhance HDAC6 expression and activity in the hippocampus of the developing brain, which can decrease synaptophysin and PSD-95 expression and cause synaptic ultrastructural damage and cognitive deficits in adulthood." (PMID 34766256, 2022). "The overexpression of circ-Vps41 could upregulate synaptophysin (Syp), thereby promoting the synaptic plasticity and alleviating cognitive impairment in aging mice." (PMID 36533129, 2022). "Furthermore, behavioral tests revealed that CPPs rescued hTau overexpression induced cognitive defects while CPPs significantly increased the fEPSP slope and synaptic proteins including synaptotagmin and synaptophysin." (PMID 30542264, 2018). "Reversal of cognitive impairment is accompanied by normalized microglial and astroglial reactivity and synaptophysin immunohistochemical staining, a normalization of gene expression of four different synaptic components, and the prevention of progressive amyloid pathology in the brain." (PMID 30254377, 2018). "However, the T294-HBc VLP-immunized mice exhibited lower levels of astrogliosis and microgliosis and higher levels of synaptophysin than adjuvant-treated mice, leading to attenuation of cognitive deficits and neuropathology in the transgenic mice." (PMID 29914543, 2018). "The level of cognitive disorder in AD patients was related to immune activity of synaptophysin." (PMID 28761498, 2017).
Cognitive impairment (continued). "Hence, our data on synaptophysin, synapsin-1 and drebrin suggest that chronic exposure to cigarette smoke leads to synaptic changes which are related to aging and cognitive impairment." (PMID 22606286, 2012). "Similarly, our Western blot data suggested that elevated circulating TMAO could downregulate synaptic plasticity-associated proteins, including synaptophysin, MAP-2, and PSD-95, which led to cognitive deficits in the rats." (PMID 36429082, 2022). "The absence of mushroom spines may underlie cognitive deficits during AD progression; SYP and PSD95 are commonly used to label pre- and post-excitatory synaptic structures." (PMID 34831483, 2021). "Therefore, impairments in signaling pathways that regulate synaptic markers such as PSD-95 and synaptophysin, and actin dynamics, such as profilin-1, could lead to the synaptic and cognitive deficits observed early in AD." (PMID 31685865, 2019). "Neob treatment attenuated ISO-induced brain inflammation as well as synaptophysin in neonatal mice by upregulating the CREB1 phosphorylation level, thereby alleviating cognitive impairment in neonatal mice." (PMID 37120983, 2023). "Studies have shown that SYN1 and SYP expression is altered in brain regions involved in learning and memory in animal models of Alzheimer’s disease (AD) and other neurodegenerative disorders, suggesting that synaptic dysfunction may contribute to cognitive impairment in these conditions." (PMID 37629211, 2023). "Reversal of cognitive deficits with VX-765 coincided with the return of normal hippocampal synaptophysin in the CA1 and improved synaptophysin levels in the CA3, DG, and cortex, respectively." (PMID 36220815, 2022). "Our previous studies have shown that the lower level of the synaptic proteins, i.e., PSD95, SYP, and BDNF, is closely related to cognitive impairment." (PMID 36760797, 2022). "Our lab’s previous study showed that the same anesthesia/surgery induced-cognitive impairment detected in the Barnes maze test and reduced hippocampus levels of PSD-95, synaptophysin, and ATP in brain tissues of mice." (PMID 34366827, 2021). "We found that the treatment with 52.8 mg/kg, but not 13.2 mg/kg or 26.4 mg/kg, of WS635 attenuated the anesthesia/surgery-induced cognitive impairment in mice and the reductions in the amounts of PSD-95, synaptophysin, and ATP in the mice brain tissues." (PMID 34366827, 2021). "Neuroinflammation induces the alternation and reduction of synaptic markers, such as synaptophysin and PSD-95, resulting in cognitive deficits." (PMID 28946610, 2017). "We showed that fluoride exposure reduced the expression of synaptic protein synaptophysin (SYN) and impaired learning and memory functions, whereas CS counteracted these alterations, suggesting its protective effect against fluoride-induced cognitive deficits." (PMID 40804089, 2025). "Likewise, synaptic proteins such as PSD95, synaptophysin, and GAP43 are closely related to cortical atrophy and cognitive impairment in dementia." (PMID 40868282, 2025). "To determine whether AS86 attenuated cognitive impairment in APP/PS1 mice by synaptic repair, we examined the presynaptic marker protein synaptophysin in CA1 area of hippocampus." (PMID 32550908, 2020). "Therefore, the present study hypothesized that WS635 attenuated the anesthesia/surgery-induced cognitive impairment and reduction in amounts of PSD-95, synaptophysin, and ATP in brain tissues of mice." (PMID 34366827, 2021). "The expression levels of TrkB, BDNF, and SYP were upregulated within the hippocampal DG of Mn-exposed mice after NSC transplantation, suggesting that NSC-induced expression of these proteins may play a critical role in rescuing the cognitive deficits induced by Mn exposure." (PMID 33815871, 2021).
Cognitive impairment (continued). "I.C.V injection of AβO induced phosphorylation of double-stranded RNA-dependent protein kinase (PKR) and eukaryotic translation initiation factor 2α (eIF2α) which triggered a decrease of synaptophysin and PSD-95 levels and cognitive impairment in WT mice, but not in TNFR−/− mice." (PMID 31128596, 2019).
Alzheimer disease (60 papers, 2009 to 2025). A progressive, neurodegenerative disease characterized by loss of function and death of nerve cells in several areas of the brain leading to loss of cognitive function such as memory and language. "RNA isolated from the cortex was analyzed by qRT-PCR to assess expression of genes involved in neurodegenerative diseases, such as Alzheimer’s disease (AD), since transgenic mouse models of AD show similarly loss of SYP+ neuropil." (PMID 40143289, 2025). "Synaptophysin plays an essential role in pre-synaptic vesicular trafficking, and its loss is often associated with neurodegenerative conditions, including Alzheimer’s disease." (PMID 40313772, 2025). "It was reported that oxidative stress is involved in synaptic loss and downregulation of synaptophysin in Alzheimer’s disease." (PMID 37605213, 2023). "Disturbance in synaptophysin expression has been associated with synaptic deficits as observed in Alzheimer’s disease." (PMID 33632243, 2021). "Synapse loss and the resulting impact on synaptophysin expression is uneven within the Alzheimer’s disease hippocampus (Heinonenet al., 1995;Honer, 2003)." (PMID 27524794, 2016). "An early event in the neuropathology of prion and Alzheimer's diseases is the loss of synapses and a corresponding reduction in the level of synaptophysin, a pre-synaptic membrane protein essential for neurotransmission." (PMID 20374666, 2010). "In post-mortem studies of the tauopathy Alzheimer’s disease, there is a biphasic synaptic protein response during disease progression, with increases in synaptophysin/syntaxin/SNAP-25 in early Braak stages and synaptic loss observed only when the disease has progressed to the neocortex." (PMID 34398211, 2022). "The loss of synapses in Alzheimer’s disease may be reflected by synaptophysin-bearing microvesicles in the cerebrospinal fluid." (PMID 34295239, 2021). "In addition, inhibition of p38-MAPK activity can revert the loss of synaptophysin induced by IL-1β in rat primary cortical neuronal cultures and in an animal model of Alzheimer’s disease." (PMID 28288671, 2017). "Therefore, neuronal loss in Alzheimer’s disease appears to mainly contribute to reduced expression of synaptophysin, which can be corrected for when expression is normalized to NSE." (PMID 25631211, 2015). "Recent studies have reported that multiple CNS insults, including PD, traumatic brain injury, and Alzheimer's disease, are associated with decreased levels of synaptophysin, a pre-synaptic membrane protein expressed in neurons that has been widely used to assess synaptic density." (PMID 24477866, 2014). "Synaptophysin is a reliable indicator of synaptic plasticity, and has previously been demonstrated to correlate well with the loss of cognitive function in mouse models with neurodegeneration and in humans with Alzheimer’s disease." (PMID 23886338, 2013). "Loss of the synaptophysin in hippocampus correlates with cognitive decline in Alzheimer's disease." (PMID 20843342, 2010). "The reduction of synaptophysin level in patients with Alzheimer’s disease and Parkinson’s disease has been reported to be attributed by the synapse loss and neuronal cell death." (PMID 37605213, 2023). "Of the CSPalpha structures analysed, 12.2 ±4.0% co-localized with synaptophysin in Alzheimer’s disease compared with control BA9 (2.6 ±1.7%) (Plaque status effect; t = 5.362, P < 0.001)." (PMID 35928052, 2022). "Few CSPalpha-positive and synaptophysin-positive structures co-localized with Aβ in Alzheimer’s disease and control brains (Braak VI, 3.7 ±1.9% and controls, 0.3 ±0.3%) (Plaque status effect; t = 2.053, P = 0.0472)." (PMID 35928052, 2022). "In post-mortem Alzheimer’s disease brain, CSPalpha protein accumulations were most commonly found 10–20 μm from the Aβ plaque core, whereas similar synaptophysin structures were generally restricted to within 10 μm of the plaque centre." (PMID 35928052, 2022).
Alzheimer disease (continued). "The percentages of synaptophysin-bearing vesicles distinguished patients with Alzheimer’s disease from the controls (AUC = 0.81)." (PMID 34295239, 2021). "In another study, mean values of SNAP-25, syntaxin, and synaptophysin levels were significantly reduced by 21–28% in the prefrontal cortex of Alzheimer’s disease patients compared with controls." (PMID 33578866, 2021). "Synaptophysin plays a crucial role in neurogenesis and neuronal interaction, particularly in degenerative diseases such as Alzheimer’s disease." (PMID 34063474, 2021). "In the brain, synaptophysin expression was shown to decrease with the progressions of Alzheimer’s disease and Parkinson’s disease." (PMID 32872333, 2020). "Synaptophysin is related to Alzheimer disease: synaptic abnormalities in the hippocampus correlate with the severity of neuropathology and memory deficit in individuals with Alzheimer disease." (PMID 31263455, 2019). "In Alzheimer's disease, the synaptic proteins synaptophysin and PSD-95 were quantified by ELISA, and the inflammatory proteins and mRNAs by MesoScale Discovery Multiplex Assays and qPCR, respectively." (PMID 30193587, 2018). "In a model of Alzheimer’s disease, Aldh2 (−/−) mice showed age-related memory deficits in the novel object recognition and Y-maze tasks and a decrease of hippocampal synaptophysin levels." (PMID 29132299, 2017). "We found that CYFIP2/synaptophysin expression was significantly decreased by ∼40% in severe Alzheimer’s disease hippocampus (t= 2.43; P< 0.05), suggesting that CYFIP2 expression declines before synapse loss occurs." (PMID 27524794, 2016). "Traditionally, synaptophysin is used as a neuropathological marker of synaptic degeneration in Alzheimer’s disease." (PMID 25631211, 2015). "Further, for investigating synaptic degeneration in Alzheimer’s disease analysis CSPalpha expression appears more suitable than assessing synaptophysin expression." (PMID 25631211, 2015). "Cognitive decline of patients with Alzheimer's disease correlates with changes in the hippocampus and the content of cortical presynaptic vesicle protein SYP content." (PMID 24459529, 2013). "Additionally, another study found that the DBS of the EC can boost synaptic activity by raising synaptophysin levels and facilitate the clearance of tau through the lysosomal pathway, resulting in a positive impact on Alzheimer’s disease." (PMID 39768683, 2024). "Likewise, there were decreased SNAP-5 levels in five brain regions of patients with Alzheimer’s disease and a 25% reduction of synaptophysin levels in the frontal cortex of patients with early Alzheimer’s disease compared with controls." (PMID 33578866, 2021). "Therefore, we believe that the increasing number of cortical neurons in the brain and the expression of synaptophysin are important in Alzheimer’s disease." (PMID 34827486, 2021). "In this sense, in the case of Alzheimer’s disease, it has been shown that the IL-1beta secreted by microglia cells decreases the synthesis of synaptophysin and that IFN-gamma can decrease the rate of synapse formation, as shown in rat-cultured sympathetic and hippocampal neurons." (PMID 30873007, 2019). "Furthermore, we also detected a downregulation of CSPalpha expression in hippocampus in mild Alzheimer’s disease when CSPalpha amounts were normalized to the synaptic marker synaptophysin." (PMID 25631211, 2015). "Previous analyses in mixed postmortem brain series found biphasic alterations of brain presynaptic markers (including synaptophysin) across age-related cognitive decline and/or Alzheimer’s disease progression, with upregulated densities at intermediate stages and reduced levels in more severe cases." (PMID 26628003, 2015). "In the first, M18 immunodensity was lower in two cortical areas in n = 32 Alzheimer’s disease cases, although after synaptophysin normalization, the authors concluded that productive synapses in Alzheimer’s disease brains might be enriched in M18." (PMID 26628003, 2015).
Alzheimer disease (continued). "In this study the process of synapse degeneration was investigated by measuring the synaptophysin content of cultured neurones incubated with the prion derived peptide (PrP82-146) or with Aβ1-42, a peptide thought to trigger pathogenesis in Alzheimer's disease." (PMID 20374666, 2010). "It is apparent that aberrant synaptic plasticity, due to abnormal expression of synaptophysin and the postsynaptic scaffolding protein, PSD-95, in the hippocampus, is functionally related to cognitive decline and Alzheimer’s disease." (PMID 35351173, 2022). "There were decreases in synaptophysin and synaptobrevin levels by approximately 30% and 10% in levels of SNAP-25 and synaptotagmin in the brain of Alzheimer’s disease patients compared with controls." (PMID 33578866, 2021). "Additional studies have demonstrated that purine derivatives promote the formation of amyloid precursor protein gene, and also stimulate the synthesis and secretion of synaptophysin (SYP), which is reported to be decreased in patients with Alzheimer’s disease." (PMID 31980673, 2020). "But also levels of synaptopodin, synaptophysin, synaptotagmins, neurogranin and GAP43 were lower in patients with Alzheimer's disease than in cognitively normal controls." (PMID 28912682, 2017). "Further, systemic administration of a CD88 antagonist has been reported to decrease the pathology, increase synaptophysin immunolabelling in the CA3 stratum lucidum and enhance behavioural outcomes in mouse models of Alzheimer's disease." (PMID 19917081, 2009). "The percentages of synaptophysin-bearing microvesicles were significantly higher in the cerebrospinal fluid of patients with Alzheimer’s disease than in the CSF of non-inflammatory neurological disease controls." (PMID 34295239, 2021). "Intriguingly, there is a specific reduction in synaptophysin levels at the earliest stages of Alzheimer’s disease with no change in the levels of other presynaptic proteins such as synaptotagmin-1 or GAP-43." (PMID 26871701, 2016). "Alzheimer's disease cortex showed significantly increased mRNA and protein levels of IL-1β, TNFα, GFAP, CD11b, cPLA2 IVA sPLA2 IIA COX-1 and COX-2, but decreased levels of pre-synaptic synaptophysin (SYP) and post-synaptic drebrin (DBN1)." (PMID 25329999, 2014). "Patients with Alzheimer's disease were found that their PSD-95 and SYP decrease in the hippocampus." (PMID 24459529, 2013). "The density of presynaptic markers of synaptic communication and plasticity, especially synaptophysin (SYP), is significantly correlated with cognitive decline and the progression of Alzheimer’s disease (AD), indicating that synaptic protection is an important therapeutic strategy for AD." (PMID 22681961, 2012). "Studies in Alzheimer's disease (AD) rats have demonstrated that increased levels of brain-derived neurotrophic factors and the administration of AM206 and miR-206 blocker, both may enhance the expression of hippocampal synaptophysin and neurogenesis and cognitive function." (PMID 36065265, 2022). "However, in a western blot analysis where synaptophysin expression was normalized to expression of a neuronal marker protein we and others did not detect reduced synaptophysin expression in Alzheimer’s disease hippocampal homogenates (Davidssonet al., 1998;Tiwariet al., 2015)." (PMID 27524794, 2016). "We used flow cytometry to analyze microvesicles carrying tau, phospho-tau-Thr181, phospho-tau-Ser202Thr205, synaptophysin, and SNAP-25 in the cerebrospinal fluid of 19 patients with Alzheimer’s disease and 15 non-inflammatory neurological disease controls." (PMID 34295239, 2021). "It has been shown that the synaptophysin expressing synapses in the hippocampus are significantly increased 24 weeks, but not 12 weeks, after TBI in a mouse model of Alzheimer’s disease, suggesting a delayed reaction of synaptogenesis after TBI." (PMID 33832542, 2021).